RAP2B (RAP2B, member of RAS oncogene family)
Description:
Small GTP-binding protein which cycles between a GDP-bound inactive and a GTP-bound active form. Involved in EGFR and CHRM3 signaling pathways through stimulation of PLCE1. May play a role in cytoskeletal rearrangements and regulate cell spreading through activation of the effector TNIK. May regulate membrane vesiculation in red blood cells.
Tractability: Small molecule: a structure with a bound ligand is known. Antibody: its Gene Ontology location is reachable by antibodies, with high confidence. PROTAC: ubiquitination databases record sites on it; its protein half-life has been measured.
Gene: Protein-coding gene on chromosome 3 (153,162,226 to 153,170,627, forward strand). Ensembl gene ENSG00000181467.
Subcellular location: Recycling endosome membrane
Pathways (Reactome):
Immune System: Neutrophil degranulation
Gene Ontology:
Molecular function: GDP binding; GTP binding; protein binding; GTPase activity; G protein activity; protein domain specific binding
Biological process: establishment of endothelial intestinal barrier; platelet activation; platelet aggregation; negative regulation of cell migration; Rap protein signal transduction; regulation of protein tyrosine kinase activity; signal transduction
Cellular component: bicellular tight junction; cell-cell contact zone; cytosol; extracellular exosome; membrane; membrane raft; plasma membrane; recycling endosome membrane; specific granule membrane; tertiary granule membrane; bounding membrane of organelle; cytoplasmic vesicle membrane; endomembrane system; recycling endosome
Genetic constraint (gnomAD): Loss-of-function variants: 6 observed, 13.83 expected, observed/expected ratio (o/e) 0.43, 90% interval 0.24 to 0.86. The upper end of that interval is the gene's LOEUF score, 0.86, which puts it in group 3 of 6, group 1 being the genes least tolerant of losing a copy. Missense variants: 137 observed, 255.77 expected, observed/expected ratio (o/e) 0.54, 90% interval 0.47 to 0.62. Synonymous variants: 118 observed, 116.05 expected, observed/expected ratio (o/e) 1.02, 90% interval 0.88 to 1.18.
Homologues: Orthologues: chimpanzee RAP2B (100% identical), dog RAP2B (100% identical), guinea pig RAP2B (100% identical), macaque RAP2B (100% identical), mouse Rap2b (100% identical), pig RAP2B (100% identical), rabbit RAP2B (100% identical), rat Rap2b (100% identical), zebrafish rap2b (96% identical), tropical clawed frog rap2b (95% identical). Paralogues in human: RAP2A (91% identical), RAP2C (84% identical), RAP1A (62% identical), RAP1B (62% identical), KRAS (46% identical), RRAS2 (46% identical), HRAS (45% identical), MRAS (45% identical), RIT1 (45% identical), NRAS (45% identical), RALA (44% identical), RRAS (44% identical), and 23 more.
Diseases named in the same sentence as RAP2B in open-access papers:
RAP2B is named in the same sentence as 29 diseases in open-access papers, as found by Europe PMC text mining. Sharing a sentence is not in itself a finding about the gene and the disease. The quoted sentences say what the papers report.
colorectal cancer (9 papers, 2017 to 2025). A primary or metastatic malignant neoplasm that affects the colon or rectum. "Rap2b, a proto-oncogene upregulated in colorectal cancer (CRC), undergoes protein S-palmitoylation at specific C-terminus sites (C176/C177)." (PMID 39277583, 2024). "Consistently, the relative mRNA level of Rap2b was significantly upregulated in colorectal carcinoma." (PMID 39277583, 2024). "Down-regulation of Rap2b sensitizes HCT116 colorectal cancer cells to apoptosis induced by adriamycin (Adr), indicating that Rap2b promotes Adr resistance in cancer cells." (PMID 28423503, 2017). "miR-361-3p downregulation may promote lymph node metastasis of T1-stage colorectal cancer via the upregulation of E2F1 or RAP2B expression." (PMID 30344797, 2018). "Subsequent validation in HCT116 cells confirmed a strong interaction between Rap2B and plectin, which was further corroborated by the co-immunoprecipitation between endogenous Rap2B and plectin in U2OS osteosarcoma cells and LOVO colorectal cancer cells." (PMID 40223002, 2025). "In colorectal cancer (CRC), Ras-related protein Rap-2B (Rap2B) was found to colocalize with plectin in both the cytoplasm and plasma membrane." (PMID 41011568, 2025).
breast carcinoma (4 papers, 2015 to 2023). "Our present study first demonstrated that significant promotions of invasion and migration by overexpression of Rap2B exist in breast cancer cell lines." (PMID 26201295, 2015). "As expected, both pharmacological inhibitors reduced Rap2B-induced effect on cell migration and invasion of breast cancer cells." (PMID 26201295, 2015). "We found that the ability of cell proliferation is decreased after Rap2B knockdown in breast cancer cells, and high proliferative activity of tumor cells is associated with increased cell-cycle transition." (PMID 26201295, 2015). "Inhibition of ERK1/2 phosphorylation was observed after Rap2B knockdown in breast cancer cells, whereas the total expression of ERK1/2 did not change." (PMID 26201295, 2015). "At the same time, our data demonstrated that overexpression of Rap2B increased cellular growth in both breast cancer cell lines." (PMID 26201295, 2015). "Meanwhile, restoration of Rap2B promotes cell migration and invasion in breast cancer cells in vitro." (PMID 26201295, 2015). "Expression of Rap2B was examined in breast cancer cell lines and human normal breast cell line using Western blot analysis." (PMID 26201295, 2015). "Using the CCK-8 cell proliferation assay, cell cycle analysis, and transwell migration assay, we also elucidated the role of Rap2B in breast cancer cell proliferation, migration, and invasion." (PMID 26201295, 2015). "In the current study, we showed that the expression level of Rap2B was higher in breast cancer cells than in normal cells." (PMID 26201295, 2015). "Taken together, these findings shed light on Rap2B as a therapeutic target for breast cancer." (PMID 26201295, 2015). "Thus, we inferred that Rap2B promotes migration and invasion of breast cancer cells via calcium related-ERK1/2 signaling pathway." (PMID 26201295, 2015). "Taken together, we infer that Rap2B might play an important role in the development of breast cancer." (PMID 26201295, 2015). "However, the mechanism through which Rap2B regulates calcium release in breast cancer cells remains to be elucidated." (PMID 26201295, 2015). "In summary, our results showed that Rap2B is expressed at high levels in breast cancer cell lines, and that Rap2B could induce calcium-dependent phosphorylation of ERK1/2." (PMID 26201295, 2015). "The RAP2B/ERK signaling pathway is one of the important pathways that contributes to cell growth and metastasis in breast cancer, glioma, and hepatocellular carcinoma." (PMID 35260078, 2022). "Further experiments are underway to evaluate the effect of Rap2B on cell migration and invasion by regulating Ca2+-related ERK1/2 signaling pathway using an in vivo tumor mouse model, hoping that we can provide a useful therapeutic strategy to help restrain the progression of breast cancer." (PMID 26201295, 2015). "However, the expression and function of Rap2B have not been fully elucidated in the development of human breast cancer." (PMID 26201295, 2015).
lung carcinoma (4 papers, 2015 to 2024). "It has been consistently reported that Rap2b is upregulated in various tumor types, including bladder cancer, lung cancer, hepatocellular carcinoma, and CRC." (PMID 39277583, 2024). "Increased level of Rap2B expression is observed in lung cancer, and is involved in tumorigenesis through activation of the NF-kappa B pathway." (PMID 26201295, 2015). "In addition, E2F1 and RAP2B were reported to promote progression and metastasis of lung cancer and their expressions was downregulated by miR-342-3p in lung cancer." (PMID 27096956, 2016). "Renewed interest in Rap2B as a novel candidate oncogene in lung cancer rapidly mounted." (PMID 26201295, 2015).
renal cell carcinoma (4 papers, 2020 to 2022). "Previous study detected that Rap2B promoted renal cell carcinoma angiogenesis via PI3K/AKT signaling pathway." (PMID 32596241, 2020). "In addition, RAP2B accelerates tumor cell progression through the PTEN/PI3K/VEGF signaling pathway in renal cell carcinoma." (PMID 35260078, 2022). "Current research on RAP2B shows that it mainly plays a role as a cancer-promoting factor in a variety of diseases, and plays an important role in the migration and invasion of tumor cells such as lung cancer 18, renal cell carcinoma 19, and prostate cancer." (PMID 33123297, 2020).
bladder cancer (3 papers, 2017 to 2024). "For example, Zhang’s group found that miR-194 suppresses proliferation, migration, and invasion by targeting RAP2B in human bladder cancer." (PMID 29163456, 2017).
glioma (3 papers, 2020 to 2022). A benign or malignant brain and spinal cord tumor that arises from glial cells (astrocytes, oligodendrocytes, ependymal cells). "Moreover, higher levels of Rap2B are associated with a poorer survival of patients with low grade gliomas." (PMID 34576182, 2021). "Rap2B has also been described to induce metalloprotease activation, promoting glioma cell invasion and migration through regulation of the ERKs’ pathway." (PMID 34576182, 2021). "In agreement with this, a recent report has shown that Rap2B also induces glioma cell proliferation." (PMID 34576182, 2021).
hepatocellular carcinoma (3 papers, 2022 to 2024). A malignant tumor that arises from hepatocytes. "For instance, in hepatocellular carcinoma cells, Rap2B has been described as an oncogene, which promotes proliferation and invasion." (PMID 39335143, 2024).
non-small cell lung carcinoma (3 papers, 2017 to 2024). A group of at least three distinct histological types of lung cancer, including non-small cell squamous cell carcinoma, adenocarcinoma, and large cell carcinoma. "Earlier, it was reported that miR-342-3p acts as a tumor suppressor in non-small cell lung cancer through repression of Ras-related protein Rap-2b (RAP2B)." (PMID 28890884, 2017). "In non-small cell lung cancer, miR-342-3p has been suggested to play a tumor-suppressive role by negatively regulating RAP2B (a member of the RAS oncogene family) and MYC transcriptional activity by targeting E2F1 (a MYC-cooperating molecule)." (PMID 28035073, 2017).
osteosarcoma (3 papers, 2020 to 2025). A usually aggressive malignant bone-forming mesenchymal neoplasm, predominantly affecting adolescents and young adults. "XIST is another potential biomarker of osteosarcoma which has been reported to modulate osteosarcoma proliferation and invasion through miR-320b/RAP2B, miR-193a-3p/RSF1, miR-21-5p/PDCD4, and miR-195-5p/YAP axis." (PMID 33639865, 2021). "Similarly, ras-related protein RAP2B was also verified as an interdependent factor of miR-320b to promote the progression of osteosarcoma." (PMID 32432698, 2020).
colon cancer (2 papers, 2024 to 2025). "Taken together, these findings demonstrate that Rap2B has a pivotal role in the development of colon cancer." (PMID 40223002, 2025). "Notably, analysis of TCGA colon cancer data revealed differential expression of Rap2b across CMS1 to CMS4, with Rap2b showing the highest expression in CMS1 compared to the other subtypes." (PMID 39277583, 2024).
melanoma (2 papers, 2022 to 2024). A malignant, usually aggressive tumor composed of atypical, neoplastic melanocytes. "RAP2B overexpression reversed the inhibitory effect on melanoma cell proliferation induced by miR-101." (PMID 36497343, 2022). "In melanoma, miR-101 regulated by lncRNA SNHG6 is negatively correlated with Ras-related protein Rap-2b (RAP2B) expression, which is a member of the RAS oncogene family." (PMID 36497343, 2022).
metastatic disease (2 papers, 2024). "In particular, PSMB4, RUVBL2, and ANKAR EV protein levels were increased in patients with metastatic disease, whereas RAP2B, SERPINA12, and IGLV4-69 abundance levels were decreased in the cEVs of patients with metastasis." (PMID 39693144, 2024). "In particular, PSMB4, RUVBL2 and ANKAR EV protein levels were increased, whereas RAP2B, SERPINA12 and IGLV4-69 abundance levels were decreased in the cEVs of patients with metastatic disease." (PMID 36993200, 2024).
pancreatic cancer (2 papers, 2022 to 2023). "Receiver operating characteristic (ROC) curve analysis suggested that TMEM43, PRPF3, and RAP2B had good diagnostic value in pancreatic cancer patients according to their prognostic value in the GSE62452, GSE16515, GSE28735, and GSE15471 datasets." (PMID 35260078, 2022). "We further demonstrated that TMEM43 promoted pancreatic cancer progression via the RAP2B/ERK pathway." (PMID 35260078, 2022). "We further assessed the effect of TMEM43 via regulating PRPF3/RAP2B axis on pancreatic cancer cell growth in vivo." (PMID 35260078, 2022). "Together, our findings suggest that PRPF3 promotes pancreatic cancer (PC) progression via the RAP2B/ERK axis." (PMID 35260078, 2022). "Collectively, these results suggest that TMEM43 mediates pancreatic cancer progression through the PRPF3/RAP2B/ERK signaling pathway." (PMID 35260078, 2022). "Kaplan–Meier curve analysis suggested that pancreatic cancer patients with high expression levels of RAP2B had worse OS." (PMID 35260078, 2022). "To confirm that TMEM43 promotes pancreatic cancer progression by RAP2B, we overexpressed RAP2B in TMEM43-silenced SW1990 cells." (PMID 35260078, 2022). "Taken together, these results suggest that TMEM43 promotes pancreatic cancer progression through the RAP2B/ERK axis." (PMID 35260078, 2022). "TMEM43 promotes migration and invasion through the PRPF3/RAP2B/ERK axis in pancreatic cancer." (PMID 37367036, 2023). "In this study, we found that silencing RAP2B could reduce the proliferation, migration, and invasion of pancreatic cancer cells via enhancing the phosphorylation of ERK." (PMID 35260078, 2022). "In addition, PRPF3 mRNA levels were significantly positively correlated with RAP2B mRNA levels using the GSE71729 dataset of pancreatic cancer." (PMID 35260078, 2022). "We demonstrated that PRPF3 knockdown could significantly inhibit cell growth, migration, invasion, and the RAP2B/ERK signaling pathway in pancreatic cancer." (PMID 35260078, 2022). "However, the function of RAP2B in pancreatic cancer is vague." (PMID 35260078, 2022). "TMEM43 mediates the RAP2B/ERK pathway by binding to and stabilizing PRPF3 to promote pancreatic cancer progression." (PMID 35260078, 2022). "Our study shows that the TMEM43/PRPF3/RAP2B/ERK axis plays a vital role in regulating cancer progression, and has a potential clinical application value for pancreatic cancer." (PMID 35260078, 2022). "To confirm that PRPF3 promoted pancreatic cancer progression via RAP2B, we overexpressed RAP2B in PRPF3-silenced SW1990 cells, and found that RAP2B overexpressing rescued RAP2B and p-ERK protein levels." (PMID 35260078, 2022). "Moreover, pancreatic cancer databases demonstrated that TMEM43 mRNA level was significantly positively associated with RAP2B mRNA expression level; we speculated that TMEM43 may regulate RAP2B expression through mediating RAP2B transcription level." (PMID 35260078, 2022). "Moreover, we demonstrated that TMEM43 promoted pancreatic cancer progression by stabilizing PRPF3 and regulating the RAP2B/ERK axis." (PMID 35260078, 2022). "Moreover, we demonstrated that the protein expression levels of RAP2B and phosphorylated ERK were decreased in PRPF3-silenced pancreatic cancer cells." (PMID 35260078, 2022). "The present study suggests that TMEM43 contributes to pancreatic cancer progression through the PRPF3/RAP2B/ERK axis, and might be a novel therapeutic target for pancreatic cancer." (PMID 35260078, 2022). "To understand the molecular mechanisms of TMEM43 in pancreatic cancer, we identified differentially expressed proteins in the context of TMEM43 knockdown using the quantitative technique of label-free protein MS, and found that RAP2B is an important downstream target of TMEM43 in pancreatic cancer." (PMID 35260078, 2022).
prostate carcinoma (2 papers, 2018 to 2022). A carcinoma that arises from epithelial cells of the prostate gland. "In addition, it was shown in prostate cancer that the effect of RAP2B is mediated at least in part by FAK-phosphorylation." (PMID 36499729, 2022).
colitis (1 paper, 2025). Inflammation of the colon. "We then investigated the role of Rap2B in the colitis-associated CRC model." (PMID 40223002, 2025). "In this study, we demonstrated that intestine-specific knockout of Rap2B suppresses the initiation and progression of colitis and CRC." (PMID 40223002, 2025). "In our study, we employed a DSS/AOM colitis and CRC induction model, and innovatively found that IEC-specific Rap2B deletion inhibited colitis progression and CRC tumorigenesis in mice." (PMID 40223002, 2025). "To examine the role of Rap2B in the development of colonic inflammation, we injected Rap2BIEC-WT mice and Rap2BIEC-KO mice with AOM, followed by administration of 2.5% DSS in their drinking water for 3 days to establish an acute colitis model." (PMID 40223002, 2025).
depression (1 paper, 2019). "Our results show that typical Rap proteins, Rap2b and Rap2a, were upregulated in the CUMS hippocampus, which indicates synaptic weakening and synaptic plasticity disturbances in depression." (PMID 31191638, 2019).
gastric cancer (1 paper, 2018). A primary or metastatic malignant neoplasm involving the stomach. "RAP2B loss may contribute dysregulation of RAS pathway which may cause genomic instability leading target interaction genes and gastric cancer progression." (PMID 30212456, 2018).
lymph node metastasis (1 paper, 2024). "The expression of Rap2B positively correlated with higher UICC/AJCC TNM stages, lymph node metastasis, and distant metastasis." (PMID 39277583, 2024). "Importantly, when comparing between CRC cases with or without lymph node metastasis, Rap2b was found to be specifically elevated in the invaded lymph nodes, suggesting a crucial role for Rap2b in the regulation of metastasis in CRC." (PMID 39277583, 2024).
rectum carcinoma (1 paper, 2024). "Further analysis suggested that a higher level of Rap2b is negatively correlated with the survival of cancer patients, particularly in rectum carcinoma." (PMID 39277583, 2024).